LRRC37A2 (leucine rich repeat containing 37 member A2)
Synonyms: FLJ45049; LRRC37
Tractability: Antibody: UniProt predicts a signal peptide or a membrane-spanning region.
Gene: Protein-coding gene on chromosome 17 (46,511,508 to 46,556,910, forward strand). Ensembl gene ENSG00000238083.
Subcellular location: Membrane
Subcellular location (Human Protein Atlas): Vesicles
Gene Ontology:
Cellular component: membrane
Genetic constraint (gnomAD): Loss-of-function variants: 7 observed, 24.61 expected, observed/expected ratio (o/e) 0.28, 90% interval 0.16 to 0.53. The synonymous counts are far from expectation, so gnomAD's model fits this gene poorly and the ratio says little. Missense variants: 133 observed, 328.74 expected, observed/expected ratio (o/e) 0.4, 90% interval 0.35 to 0.47. Synonymous variants: 51 observed, 104.29 expected, observed/expected ratio (o/e) 0.49, 90% interval 0.39 to 0.62.
Homologues: Orthologues: chimpanzee LRRC37A3 (95% identical), rat Prp2l1 (42% identical), mouse Lrrc37a (41% identical), mouse Lrrc37 (39% identical), rat Lrrc37a (39% identical). Paralogues in human: LRRC37A (99% identical), LRRC37A3 (94% identical), LRRC37B (37% identical).
Diseases named in the same sentence as LRRC37A2 in open-access papers:
LRRC37A2 is named in the same sentence as 8 diseases in open-access papers, as found by Europe PMC text mining. Sharing a sentence is not in itself a finding about the gene and the disease. The quoted sentences say what the papers report.
breast carcinoma (2 papers, 2023 to 2024). "Of those, we present five proteins (CD160, DNPH1, LAYN, LRRC37A2 and TLR1) that show a potential causal role in breast cancer risk with confirmatory results in independent cohorts." (PMID 37996402, 2023). "In light of these intricate interconnections, it is plausible that LRRC37A2, through its involvement in the pathological processes of Parkinson's disease and breast cancer, may directly or indirectly impact bone metabolism, which may explain the genetic link between LRRC37A2 and BMD." (PMID 39526243, 2024).
Parkinson disease (2 papers, 2022 to 2024). A progressive degenerative disorder of the central nervous system characterized by loss of dopamine producing neurons in the substantia nigra and the presence of Lewy bodies in the substantia nigra and locus coeruleus. "Several studies suggested that LRRC37A2 is implicated in epilepsy, epileptic encephalopathy, and Parkinson’s disease, while the effect on DLBCL has never been reported." (PMID 35774514, 2022).
schizophrenia (1 paper, 2026). A major psychotic disorder characterized by abnormalities in the perception or expression of reality. "In particular, the expression of SPPL2C, MAPT, LRRC37A2, and ARL17A was significantly associated with schizophrenia as well as with MD and λ1 of the right ICP." (PMID 41522603, 2026). "Representative associations were observed for SPPL2C, MAPT, LRRC37A2, and ARL17A, whose expression in the brain was significantly associated with schizophrenia as well as with MD and λ1 of the right inferior cerebellar peduncle (ICP)." (PMID 41522603, 2026).
LRRC37A2 also shares sentences with these, for which no sentence is quoted: Alzheimer disease (1 paper); cognitive decline (1); COVID-19 (1); epilepsy (1); Epileptic encephalopathy (1).